LEP (leptin)
Diseases named in the same sentence as LEP in open-access papers (continued):
Sharing a sentence is not in itself a finding about the gene and the disease.
colon carcinoma (continued). "Among various factors secreted at high levels by obese AT, we assessed whether leptin may potentially participate in lowering of mitochondrial respiration in the colon cancer cell line HCT116." (PMID 24073224, 2013). "Indeed, our data present evidence for metabolic alterations induced by leptin in HCT116 colon cancer cells that are similar to the ones observed by the obese CM." (PMID 24073224, 2013). "Moreover, we find that leptin can be a key molecular signal mediating the interaction between AT and colon cancer cells." (PMID 24073224, 2013). "Moreover, our results point for a direct link between the AT and colon cancer cells, as demonstrated by the involvement of leptin, a specific secretion of the adipocytes themselves." (PMID 24073224, 2013). "Interestingly, we found a significant difference in leptin concentrations of male patients with colon carcinoma vs. patients with rectal carcinoma." (PMID 23173608, 2012). "Leptin stimulates proliferation of colon cancer cell lines in vitro." (PMID 23056418, 2012). "Moreover, leptin counteracted cytotoxic effects of 5-fluorouracil, a common colon cancer therapeutic agent." (PMID 22363883, 2011). "Taken together, these results of this study suggest that adipokines, in particular resistin and leptin may be involved in development and progression of colon cancer." (PMID 21254741, 2010). "We found significantly lower serum leptin levels in colon cancer patients as compared to controls." (PMID 21254741, 2010). "Taken together, these results of this study suggest that adipokines, in particular resistin and leptin might be involved in development and progression of colon cancer." (PMID 21254741, 2010). "However, in various human colon carcinoma cells leptin significantly stimulated the locomotory behaviour of the cells." (PMID 20030801, 2009). "Recently, we could demonstrate in our own studies, that adiponectin and leptin alone significantly stimulated the migration of SW480 colon carcinoma cells, respectively, whereas the combination of both negated these pro-migratory effects (data not shown)." (PMID 20030801, 2009). "Thus, further studies would be necessary for clarify the relationship leptin and colon cancer in clinical study." (PMID 21566743, 2008). "In the study, leptin levels were lower in colon cancer patients despite lack of weight loss and BMI measurements comparable to that of control subjects." (PMID 21566743, 2008). "Leptin has been shown to inhibit serum-starvation and celecoxib-induced apoptosis in HT-29, T84 and Caco-2 colon cancer cells via Akt-dependent pathways and inhibit butyrate-induced apoptosis in HT-29 cells, although in the latter study the effect of Akt was not examined." (PMID 17559672, 2007). "Moreover, other studies show that expression of IL-8 can induce migration and recruitment of CXCR1 (+) CD8 (+) T cells in inflammatory areas and using the Leptin trigger of the mouse model of colon cancer can promote the recruitment of T cells and enhance immune response." (PMID 36532065, 2022). "But in our study, LEP has not been found to be significantly associated with colon cancer stage." (PMID 34094943, 2021). "Notably, a study in colon cancer demonstrated that leptin could upregulate miR-4443 to restrain TRAF4 and NCOA1 expression, leading to decreased cancer invasion." (PMID 33799880, 2021). "There is accumulating evidence that leptin signaling might be involved in colon cancer." (PMID 29593647, 2018). "In colon cancer, the expression of Leptin is associated with negative lymph node metastasis." (PMID 21342584, 2011). "Previous studies have shown that LEP up-regulates miR-4443, thereby suppressing NCOA1 and TRAF4, and decreasing the invasiveness of human colon cancer cells." (PMID 37282602, 2023).
colon carcinoma (continued). "Through binding to the receptor LEPR, leptin/LEPR signaling has been shown to be related to the progression of a large number of cancers, such as pancreas and colon cancers." (PMID 35115495, 2022). "A similar outcome was published by another group using leptin-derived peptide (LP16, 91–110 of leptin) to reduce tumor growth in a C26 colon carcinoma tumor-bearing mouse model." (PMID 33799880, 2021). "In contrast to leptin, adiponectin protects against chronic inflammation-induced colon cancer (CICC) and demonstrates beneficial effects on colon cancer." (PMID 33167521, 2020). "We collected 44 surgically resected colon cancer tissues along with normal adjacent colon tissue (NACT) from a sample of CRC patients from the Malaysian population and looked for leptin and leptin receptors using immunohistochemistry (IHC)." (PMID 31592340, 2019). "Since we previously found the involvement of leptin in inhibiting mitochondrial respiration and gene expression in HCT116 human colon cancer cells, we also addressed this issue in the present study." (PMID 26472027, 2015). "In colon cancer cells (HT-29), EGF-induced PI-3K/STAT3 signaling was suggested as an essential pathway regulating VEGF and leptin expression." (PMID 24202338, 2013). "In these EGF-responsive colon cancer cells, EGF induced STAT3 binding to VEGF and leptin promoters and stimulated leptin and VEGF mRNA and protein synthesis." (PMID 24202338, 2013). "In contrast, another study noted that serum leptin levels in patients with colon cancer were significantly decreased despite lack of weight loss and BMI measurements when compared to control subjects." (PMID 29593647, 2018). "Until now, no data existed about a leptin-mediated regulation on cytotoxic effects of NK cells against colon tumor cells." (PMID 28357137, 2017). "Finally, as it was previously shown that leptin concentration in CM was directly correlated with BMI of adipose tissue donors, thus we determined if leptin secreted from adipose tissue explants could mediate the effect of the obese-CM on colon cancer cell respiration." (PMID 24073224, 2013). "In a previous study from our laboratory, lifetime consumption of SPI lowered: tumor incidence, body weight accretion and serum insulin and leptin levels in a non-obese, rat model of colon cancer." (PMID 23056418, 2012). "However, MAT explants obtained from Crohn's disease patients had a significant higher level of expression of inflammatory mediators (IL-6, MCP-1) and leptin and adiponectin when compared to MAT obtained from patients with colon carcinomas (n = 5; # p<0.05)." (PMID 21829567, 2011). "Furthermore, C/EBP-β regulates energy balance, and promotes growth of colon cancer cells in part via activation of IGF-1, insulin, and leptin." (PMID 21048943, 2010). "Likewise, leptin was found to promote OXPHOS and ATP production in colon cancer cells." (PMID 33535537, 2021). "Moreover, leptin has been shown to interfere with non-hormonal therapies, since the in vitro cytotoxic effect of 5-fluorouracil (5 FU) on colon cancer cells is diminished in presence of leptin." (PMID 23554900, 2013). "LPS increased COX2 and TNFSF10 mRNA levels but did not exhibit significant effect on HuA, LEPTIN and TNF mRNA levels in the human colon cancer cells." (PMID 37705049, 2023). "One study showed the potential of a leptin-derived peptide formulation in decreasing tumor growth and improved survival in BALB/c mice bearing C26 colon carcinoma than those treated with the same, non-Ob-R specific formulation." (PMID 36361914, 2022).
Sepsis (84 papers, 2007 to 2025). Sepsis is defined as life-threatening organ dysfunction caused by a dysregulated host response to infection. "In leptin-deficient mice, exogenous leptin administration improved survival rates during sepsis by reducing systemic IL-6 levels and controlling inflammation." (PMID 40095902, 2025). "The magnitude of the initial rise in leptin is associated with sepsis severity but, interestingly, survivors have higher levels than non-survivors." (PMID 37144447, 2023). "For instance, leptin-deficient ob/ob mice with sepsis had more severe disease and higher mortality compared to the respective controls, and this was improved by leptin replacement." (PMID 37238973, 2023). "We find the results from the current review to be of great importance due to the possible therapeutic role of leptin analogs in states of leptin deficiency associated with infectious diseases or sepsis." (PMID 33907162, 2021). "In a study conducted by Bornstein and colleagues, it was revealed that there is a loss of diurnal rhythm in cortisol and leptin secretion in patients who survived acute sepsis." (PMID 33907162, 2021). "They demonstrated that administration of exogenous leptin decreased the death risk in sepsis at early and late stages." (PMID 33907162, 2021). "In leptin-deficient mice exogenous leptin modulated the immune response against sepsis and tremendously improved the survival rates by reducing IL-6 levels in serum and thereby controlled systemic inflammation." (PMID 32824322, 2020). "Independent of dialysis, kidney dysfunction is an important risk factor for sepsis, due to its association with the presence of uremic compounds (leptin, advanced glycation end products, and guanidine) that interfere with immune cells." (PMID 32160890, 2020). "Systemic leptin replacement modulated the immune response against sepsis and increased survival in both leptin-deficient and wild-type mice." (PMID 29868503, 2018). "For that reason, serum leptin levels have also been proposed as diagnostic tools, biomarkers and prognostic factors to predict the development of sepsis and its outcomes." (PMID 30618812, 2018). "Here, we found levels of insulin and leptin, a hormone and an adipokine associated with metabolic (predominantly anabolic) and immune functions were lower in sepsis survivors." (PMID 29326685, 2017). "We have shown previously that the microvascular inflammation in early sepsis in leptin deficient ob/ob, leptin resistant db/db and melanocortin 4 receptor knock out mice associated obese phenotypes are similar." (PMID 27500833, 2016). "The inability of the lean mice to increase leptin in sepsis caused a state of hypoleptinemia which likely led to hypothermia." (PMID 25844479, 2015). "Leptin deficiency induces hypothermia as shown in leptin-deficient ob/ob mice and hypoleptinemic states in sepsis are connected to hypothermia and increased risk of infections." (PMID 25844479, 2015). "Based on the associations between leptin and markers of organ dysfunction, it was clear that leptin has the potential to facilitate prognosis and guide the treatment of sepsis." (PMID 24669245, 2014). "The adipose tissue-derived hormone leptin has a well-characterised role in energy homoeostasis, but has also been suggested to play a pathogenic role in sepsis." (PMID 24578293, 2014). "The present study was conducted to determine the role of serum leptin in the early diagnosis of sepsis and to establish a diagnostic model for sepsis." (PMID 24669245, 2014). "Earlier reports suggested that high lepin levels are associated with increased survival in sepsis and septic shock, whereas several other reports fail to show a correlation between leptin and sepsis." (PMID 22272381, 2012). "• Leptin monitoring is associated with a high degree of efficacy and specificity for differentiation of sepsis." (PMID 20230641, 2010). "Bornstein and associates found that plasma leptin levels are increased in survivors of acute sepsis." (PMID 17349033, 2007).
Sepsis (continued). "However, leptin levels decrease in persistent or prolonged clinical sepsis, likely due to a loss of fat mass." (PMID 39968295, 2025). "Notably, according to the leptin-induced increase in survival, leptin administration decreased the risk for death associated with endotoxemia at early and late times within the course of sepsis." (PMID 30618812, 2018). "Leptin-deficient mice and mice rendered leptin-deficient by fasting exhibit impaired pulmonary bacterial clearance and enhanced lethality during pulmonary tuberculosis, bacterial pneumonia, and sepsis." (PMID 30534129, 2018). "These add up on the established molecules such as Resistin, PAI-1, Adiponectin, Leptin and AGEs (Advanced Glycation End-products) that are prime examples underlying inflammation, putatively accounting for some of the apparent links between sepsis and MetS." (PMID 29922126, 2018). "Leptin deficiency is highly fatal in mice suffering from sepsis due to severe organ damage." (PMID 29868503, 2018). "Despite that plasma levels of leptin were increased and positively correlated with proinflammatory cytokines during sepsis and further associated with increased survival of sepsis, few studies have addressed the influence of innate immunity on adiponectin and leptin in humans." (PMID 26664879, 2015). "Leptin deficiency increases susceptibility to endotoxic shock and sepsis." (PMID 25844479, 2015). "The present study demonstrated that leptin, in combination with other independent factors, such as temperature, platelet and WBCs and heart rate, may be an effective diagnostic model of sepsis." (PMID 24669245, 2014). "The data indicate that leptin is associated with sepsis and a subsequent ROC curve analysis revealed that leptin, as an independent indicator, may differentiate septic patients from controls." (PMID 24669245, 2014). "The sum of these findings underlines the need to further study the role of LEP in sepsis." (PMID 21943151, 2011). "• Sepsis was associated with low circulating leptin levels throughout an intensive care stay." (PMID 19589139, 2009). "Indeed, sex-related differences related to leptin and disease outcome triggered by infections may exist, as a prospective study documented high leptin levels at baseline to predispose individuals to sepsis." (PMID 37238973, 2023). "The amplitude of these changes until return to initial level has, however, individual variation and may reflect adaptive particularities with prognostic potential (e.g. blunted postoperatory leptin increase meaning the overlap of sepsis and/or a higher mortality risk)." (PMID 31425509, 2019). "Importantly, recent studies reported that serum leptin level may be used as a promising diagnostic or prognostic marker for critical illness sepsis that is triggered by an infective agent such as bacteria, viruses, fungi, or parasites." (PMID 30534129, 2018). "Thus, leptin may be utilized as a potential diagnostic marker of sepsis with a similar efficacy to other markers, such as CRP and PCT." (PMID 24669245, 2014). "Thus, the possible pathogenic role for leptin in sepsis may be linked to leptin-induced suppression of the HPA axis impairing the protective role of the HPA axis in sepsis." (PMID 24578293, 2014). "Evidence suggests that the adipokine leptin may play a pathogenic role in sepsis." (PMID 24578293, 2014). "Together, this suggests that the marked increase and loss of circadian rhythm in circulating glucocorticoids and the increase in IL-6 likely drive the increase in leptin levels in early sepsis." (PMID 39968295, 2025). "Leptin is a stress-related hormone and affects the body’s response to injury in sepsis in addition to allowing fatty tissue stores in the periphery to communicate with the central nervous system." (PMID 39838305, 2025). "Major non-HPA hormones dysregulated during sepsis in humans and models of polymicrobial sepsis include melatonin and leptin." (PMID 39968295, 2025).
Sepsis (continued). "Leptin also plays a crucial role in combating sepsis, a severe inflammatory response that can lead to organ failure and death." (PMID 40095902, 2025). "In particular, adiponectin, leptin, resistin, visfatin, chemerin, and omentin increase at sepsis onset, and their kinetics in the early phase of sepsis are associated with sepsis mortality." (PMID 38540711, 2024). "Only a few studies have investigated the relationships between leptin levels and infection/sepsis in humans." (PMID 35011102, 2022). "They found that the patient’s leptin level was low at the time of the infection and was correlated with the severity of sepsis." (PMID 35011102, 2022). "Leptin levels also increase after sepsis and septic shock, probably as a host mechanism to defend against bacterial infection." (PMID 34017323, 2021). "The time aspect seems important, since leptin levels usually increase during the initial phase of sepsis, followed by a subsequent decline." (PMID 35052684, 2021). "Plasma leptin levels were analyzed in a cohort of participants in a previous health survey and who later developed sepsis." (PMID 35052684, 2021). "The multiple effects of leptin are of growing interest, but further studies are needed to elucidate the role of leptin signalling in infectious diseases and sepsis." (PMID 33907162, 2021). "The aim of the current article was to provide an overview of the medical literature on the correlations between variations of leptin levels and infectious diseases and sepsis." (PMID 33907162, 2021). "Monitoring circulating total leptin levels has been proven to have an important role in distinguishing sepsis from SIRS with an etiology other than infection." (PMID 33907162, 2021). "Overall, all the patients presented with elevated TREM-1 and OPN and most had elevated NGAL and leptin levels; for all, a gradual decrease upon resolution of sepsis was observed." (PMID 34659208, 2021). "It is taken into consideration the potential preventive therapy with exogenous recombinant leptin against sepsis in critically ill patients." (PMID 33907162, 2021). "Over the past decade, the role of total serum leptin in infectious diseases and sepsis has been explored in experimental models on mice and in few human studies." (PMID 33907162, 2021). "There is a need for further studies to demonstrate the specificity and sensitivity of leptin in the early diagnosis of sepsis and the need to measure serum leptin levels in routine evaluation of the critical patient." (PMID 33907162, 2021). "This review aims to evaluate the role of serum leptin in the early diagnosis of sepsis and as a predictive factor of its evolution." (PMID 33907162, 2021). "We performed an extensive literature search in PubMed and Google Scholar databases, using keywords to identify articles related to leptin in infectious diseases and sepsis." (PMID 33907162, 2021). "The aim of the current article is to provide an overview of the medical literature on the correlations between variations of leptin levels and infectious diseases and sepsis." (PMID 33907162, 2021). "There is an increase in leptin levels in patients with sepsis and a decrease in leptin levels in patients with an unfavourable outcome." (PMID 33907162, 2021). "We find the results from the current review to be of great importance due to the possible therapeutic role of leptin analogs in infectious diseases and sepsis." (PMID 33907162, 2021). "Leptin, a cytokine that is produced and stored in adipocytes, is believed to have a protective role in the acute systemic inflammation seen with sepsis by regulating cell-mediated immunity, endothelial activation, and cytokine release." (PMID 32190482, 2020). "Some studies suggest that sepsis alters the CNS effects of leptin and ghrelin, which are integral in central modulation of metabolism." (PMID 32676795, 2020).